POLE2 (DNA polymerase epsilon 2, accessory subunit)
Description:
Accessory component of the DNA polymerase epsilon complex. Participates in DNA repair and in chromosomal DNA replication (By similarity).
Synonyms: DPE2
Tractability: Small molecule: an approved drug acts on it; a structure with a bound ligand is known. PROTAC: ubiquitination databases record sites on it.
Gene: Protein-coding gene on chromosome 14 (49,643,555 to 49,688,422, reverse strand). Ensembl gene ENSG00000100479.
Subcellular location: Nucleus
Subcellular location (Human Protein Atlas): Nuclear bodies; Nucleoplasm; Vesicles
Pathways (Reactome):
DNA Repair: Dual Incision in GG-NER; Dual incision in TC-NER; Gap-filling DNA repair synthesis and ligation in GG-NER; Gap-filling DNA repair synthesis and ligation in TC-NER; HDR through Homologous Recombination (HRR); PCNA-Dependent Long Patch Base Excision Repair; Recognition of DNA damage by PCNA-containing replication complex; Termination of translesion DNA synthesis
DNA Replication: Activation of the pre-replicative complex; DNA replication initiation
Gene Ontology:
Molecular function: protein binding; DNA-directed DNA polymerase activity; DNA binding
Biological process: DNA-templated DNA replication; DNA repair; DNA replication; error-prone translesion synthesis; DNA metabolic process
Cellular component: epsilon DNA polymerase complex; nuclear body; nucleoplasm; chromosome; nuclear lumen; nucleus
Genetic constraint (gnomAD): Loss-of-function variants: 6 observed, 3.92 expected, observed/expected ratio (o/e) 1.53, 90% interval 0.76 to 1.93. That is too few expected variants to judge how well the gene tolerates losing a copy. Missense variants: 78 observed, 46.7 expected, observed/expected ratio (o/e) 1.67, 90% interval 1.38 to 1.93. Synonymous variants: 37 observed, 19.08 expected, observed/expected ratio (o/e) 1.94, 90% interval 1.41 to 1.98.
Homologues: Orthologues: chimpanzee POLE2 (99% identical), macaque POLE2 (98% identical), pig POLE2 (94% identical), dog POLE2 (94% identical), guinea pig POLE2 (92% identical), rat Pole2 (91% identical), mouse Pole2 (90% identical), tropical clawed frog pole2 (81% identical), rabbit POLE2 (53% identical), zebrafish pole2 (47% identical), Drosophila melanogaster PolE2 (41% identical), Caenorhabditis elegans pole-2 (30% identical).
Diseases named in the same sentence as POLE2 in open-access papers:
POLE2 is named in the same sentence as 38 diseases in open-access papers, as found by Europe PMC text mining. Sharing a sentence is not in itself a finding about the gene and the disease. The quoted sentences say what the papers report.
colorectal cancer (13 papers, 2018 to 2025). A primary or metastatic malignant neoplasm that affects the colon or rectum. "POLE2 mutations have been associated with colorectal cancer, but the POLE2 CNV related to hereditary cancer syndrome is a new finding." (PMID 37628631, 2023). "We observed a variant in POLE2, which was predicted as damaging by all in silico tools, in a patient who had colorectal cancer at age 59 years old." (PMID 29641532, 2018). "DNA polymerase epsilon subunit 2 (POLE2) is a nuclear DNA polymerase subunit that is commonly associated with DNA repair and is aberrantly expressed in cancer., such as renal cell carcinoma, colorectal cancer, bladder cancer and lung adenocarcinoma." (PMID 38734676, 2024). "Notably, CHEK1 inhibition is synthetically lethal with loss of B-Family DNA Polymerases like POLE2 in lung cancer and colorectal cancer cells." (PMID 34853396, 2021). "The missense variant in POLE2 occurred in an individual who had colorectal cancer at age 59 years." (PMID 29641532, 2018). "Separately, the DNA polymerase epsilon 2 accessory subunit (POLE2), which modulates cellular proliferation mechanisms, has been identified as an overexpressed gene in colorectal cancer." (PMID 41614789, 2025). "Consistent with the idea that replication stress dictates CHKi response, silencing of multiple DNA polymerase isoforms, including POLA1, POLE, and POLE2, enhances replication stress and increases CHK1i sensitivity in lung and colorectal cancer cell lines." (PMID 35444937, 2022). "Previous studies showed that POLE2 is overexpressed in many cancers, such as lung adenocarcinoma, breast cancer, colorectal cancer and esophageal squamous cell carcinoma (ESCC), and it can promote tumor development." (PMID 33644060, 2021). "On the other hand, POLE2 had been previously reported to be highly expressed in breast cancer, colorectal cancer, cervical cancer and bladder cancer." (PMID 35173608, 2021). "Currently, POLE2 have reported to be abnormally expressed in breast cancer, colorectal cancer, mantle cell lymphoma, bladder cancer and lung adenocarcinoma." (PMID 33644060, 2021). "In addition, abnormalities of POLE2 have also been found in human tumors, such as colorectal cancer." (PMID 32831648, 2020). "Similarly, DNA replication gene knockout may improve CHK1i activity, by inhibiting POLA1, POLE, and POLE2 genes in a siRNA screen performed on lung and colorectal cancer cells showing low sensitivity to CHK1i60." (PMID 38555285, 2024).
lung adenocarcinoma (8 papers, 2020 to 2024). A carcinoma that arises from the lung and is characterized by the presence of malignant glandular epithelial cells. "The POLE2 knockdown cells exhibit inhibited the ability of cell clone formation, proliferation, invasion and immigration, which is consistent with findings in lung adenocarcinoma cells 53, indicating that POLE2 is a bladder tumor promotor." (PMID 38370377, 2024). "It is also the first time to confirm the significance and relationship of FOXM1 and its target gene POLE2 in lung adenocarcinoma." (PMID 35173608, 2021). "Berberine inhibited the proliferation of lung adenocarcinoma cells by interfering with the expression of POLE2 involved in DNA replication mediated by transcription factor FOXM1." (PMID 35173608, 2021). "In conclusion, berberine intervened the survival of lung adenocarcinoma cells by inhibiting the expression of POLE2 mediated by FOXM1." (PMID 35173608, 2021). "Downregulation of POLE2 expression could significantly inhibit the proliferation and colony formation and induce apoptosis of lung adenocarcinoma cell." (PMID 32831648, 2020). "However, the specific molecular mechanism of berberine interfering with POLE2 expression in lung adenocarcinoma (LUAD) is still unknown to a great extent." (PMID 35173608, 2021). "This is the first study on the mechanism of berberine in the treatment of lung adenocarcinoma by regulating FOXM1 and POLE2 mediated by FOXM1." (PMID 35173608, 2021). "In addition, we demonstrated that the therapeutic target of berberine was to inhibit the expression of FOXM1 and POLE2 mediated by FOXM1, so as to intervene the survival of lung adenocarcinoma (Overview of this study)." (PMID 35173608, 2021).
breast carcinoma (7 papers, 2017 to 2024). "An AATT deletion in intron 18 of the POLE2 subunit of Polymerase ε is associated with breast cancer, and POLE2 is suggested to contribute to lapatinib resistance in HER2+ breast cancer patients with acquired lapatinib resistance." (PMID 33662042, 2021). "Altered expression of HMGA2, POLE2 and TRIB3 was predictive of survival among members of the Metabric breast cancer cohort." (PMID 30763339, 2019). "Of the 23 co-expressed mRNAs identified through RNA-seq, we demonstrated that overexpression of HMGA2, POLE2 and TRIB3 reduced metastasis-free survival in Metabric Breast Cancer cohort from TCGA, as observed by Kaplan Meier analysis." (PMID 30763339, 2019). "In conclusion, the overexpression of AURKB, GINS2, MCM10, UHRF1, POLE2, SPC24, and E2F2 in HER2-positive breast cancer patients with ALR showed that these hub genes could be potential prognostic biomarkers in such patients." (PMID 33013420, 2020).
bladder cancer (5 papers, 2019 to 2024). "Based on the random forest analysis of the 10 PEGs, we discovered that POLE2 was the most significant gene differentiating bladder cancer tissues and adjacent normal tissues, implying that it plays an extremely important role in BLCA progression." (PMID 38370377, 2024). "In previously published articles, POLE2 has been identified as part of a set of molecular biomarkers or target genes in metastatic advanced bladder cancer patients as well it is one of the genes in a model to predict survival in mantle-cell lymphoma." (PMID 30763339, 2019). "Finally, we assessed the impact of POLE2 expression on the resistance to cisplatin, a commonly used chemotherapy drug for bladder cancer." (PMID 38370377, 2024).
renal cell carcinoma (5 papers, 2021 to 2024). "The aim of this study is to investigate the biological functions and the underlying mechanisms of DNA polymerase epsilon subunit 2 (POLE2) in renal cell carcinoma (RCC)." (PMID 33644060, 2021). "Relationship between POLE2 expression and tumor characteristics in patients with renal cell carcinoma." (PMID 33644060, 2021). "POLE2 expression in renal cell carcinoma and para-carcinoma tissues detected by immunohistochemistry." (PMID 33644060, 2021). "previously demonstrated that POLE2 expression was elevated in renal cell carcinoma (RCC) tissues and that higher POLE2 level correlated with poor prognosis." (PMID 38070189, 2024).
Fanconi anemia (4 papers, 2013 to 2022). Fanconi anemia (FA) is a hereditary DNA repair disorder characterized by progressive pancytopenia with bone marrow failure, variable congenital malformations and predisposition to develop hematological or solid tumors.
glioblastoma (4 papers, 2022 to 2024). The most malignant astrocytic tumor (WHO grade IV). "A very recent study also identified an abnormal elevation of POLE2 in human glioblastoma tissues, and they determined that knocking down POLE2 inhibited the malignancies of glioblastoma." (PMID 38070189, 2024). "POLE2 promotes the malignant phenotype of glioblastoma by promoting AURKA-mediated stabilization of FOXM1." (PMID 37880682, 2023).
esophageal squamous cell carcinoma (3 papers, 2021 to 2024). Esophageal squamous cell carcinoma (ESCC) is a type of esophageal carcinoma (EC) that can affect any part of the esophagus, but is usually located in the upper or middle third. "Recently, an in vivo study indicated a positively correlation between POLE2 and tumor formation in esophageal squamous cell carcinoma." (PMID 38627379, 2024). "Studies show that POLE2 is highly expressed in patients with esophageal squamous cell carcinoma (ESCC)." (PMID 35780178, 2022).
lung carcinoma (3 papers, 2019 to 2024).
gastric cancer (2 papers, 2019 to 2024). A primary or metastatic malignant neoplasm involving the stomach. "Meanwhile, POLE2 level in gastric cancer patients with lymph node metastasis was higher than those without metastasis." (PMID 38070189, 2024). "Human gastric cancer cells were infected with lentiviral vectors to knock down or overexpress POLE2, and cell ferroptosis was detected." (PMID 38070189, 2024). "POLE2 knockdown was induced, while POLE2 overexpression inhibited ferroptosis in human gastric cancer cells, thereby controlling the malignant phenotypes of gastric cancer." (PMID 38070189, 2024). "In general, our findings first reveal that POLE2 overexpression inhibits ferroptosis of human gastric cancer cells through activating the NRF2/GPX4 pathway and provide a theoretical principal of molecular therapy for gastric cancer through inhibiting POLE2." (PMID 38070189, 2024). "ROS generation and lipid peroxidation were also reduced in POLE2‐overexpressed human gastric cancer cells, followed by improvements of PUFAs oxidation and membrane destruction." (PMID 38070189, 2024). "In general, our findings reveal that POLE2 overexpression inhibits ferroptosis of human gastric cancer cells through activating the NRF2/GPX4 pathway and provide a theoretical basis of molecular therapy for gastric cancer through inhibiting POLE2." (PMID 38070189, 2024). "As expected, the inhibitory effects of ROS generation, lipid peroxidation and PUFAs oxidation in human gastric cancer cells with POLE2 overexpression were also blunted by either NRF2 or GPX4 silence." (PMID 38070189, 2024). "In our study, we found that POLE2 expression was elevated in human gastric cancer tissues and cells and that POLE2 knockdown significantly induced ferroptosis of gastric cancer cells, thereby preventing the progression of gastric cancer." (PMID 38070189, 2024). "Collectively, these results imply that POLE2 overexpression inhibits ferroptosis of human gastric cancer cells through activating the NRF2/GPX4 pathway." (PMID 38070189, 2024). "POLE2 expression was elevated in human gastric cancer cells and tissues and closely correlated with clinicopathological features in gastric cancer patients." (PMID 38070189, 2024). "In this study, POLE2 expression was found to be elevated in gastric cancer and closely correlated with the clinicopathological features of gastric cancer patients." (PMID 38070189, 2024). "Herein, we intend to determine the involvement and mechanism of POLE2 in ferroptosis of gastric cancer." (PMID 38070189, 2024). "POLE2 mRNA level was elevated in human gastric cancer cells compared to normal human gastric epithelium cells, and POLE2 mRNA as well as protein levels were also increased in human gastric cancer tissues." (PMID 38070189, 2024). "Taken together, we speculate that POLE2 knockdown induces ferroptosis and subsequently mitigates the malignancies of human gastric cancer cells." (PMID 38070189, 2024). "ROS and MDA levels were elevated in POLE2‐silenced gastric cancer cells." (PMID 38070189, 2024). "Amazingly, POLE2 knockdown could suppress proliferation, migration and invasion of human gastric cancer cells." (PMID 38070189, 2024). "In addition, gastric cancer patients with a higher POLE2 mRNA level exhibited advanced TNM stage and clinicopathological grade." (PMID 38070189, 2024). "Given the role of POLE2 in gastric cancer and other tumours, we speculated that developing pharmacological inhibitors or neutralising antibody target for POLE2 would be of great therapeutic interest to treat human gastric cancer." (PMID 38070189, 2024). "POLE2 knockdown was induced, while POLE2 overexpression inhibited ferroptosis of human gastric cancer cells, thereby modulating the malignant phenotypes of gastric cancer." (PMID 38070189, 2024). "We thus determined whether the NRF2/GPX4 pathway was essential for POLE2 overexpression‐mediated inhibition on ferroptosis in gastric cancer." (PMID 38070189, 2024).
gastric cancer (continued). "POLE2 overexpression significantly increased NRF2 expression and activity in the two gastric cancer cells." (PMID 38070189, 2024). "Mechanistic studies revealed that POLE2 overexpression elevated NRF2 expression and activity and subsequently activated GPX4, which then prevented ferroptosis of human gastric cancer cells." (PMID 38070189, 2024). "POLE2 overexpression inhibits ferroptosis in human gastric cancer cells through activating NRF2/GPX4 pathway, and inhibiting POLE2 may be a crucial strategy to treat gastric cancer." (PMID 38070189, 2024). "Yet, we herein found no alteration of intracellular iron level in human gastric cancer cells with POLE2 knockdown or overexpression." (PMID 38070189, 2024). "Mechanistic studies revealed that POLE2 overexpression elevated NRF2 expression and activity and subsequently activated GPX4, which then prevented lipid peroxidation and ferroptosis in human gastric cancer cells." (PMID 38070189, 2024). "DNA polymerase epsilon subunit 2 (POLE2) plays indispensable roles in tumorigenesis; however, its involvement and molecular basis in ferroptosis and gastric cancer are not clear." (PMID 38070189, 2024).
glioma (2 papers, 2021 to 2022). A benign or malignant brain and spinal cord tumor that arises from glial cells (astrocytes, oligodendrocytes, ependymal cells). "Notable genes with SNV-associated increased expression include TERT, COPS3, POLE2 and HDAC2—involving multiple cancer types—MYC, BCL2, PIM1 and IGLL5—involving lymphomas—and CYHR1—involving pediatric low-grade gliomas." (PMID 33554123, 2021).
combined immunodeficiency (1 paper, 2020). A broad classification of inherited disorders presenting at birth that affect both the cell-mediated and humoral aspects of the immune response. "Mutations in POLE2 have been reported in patients with combined immunodeficiency, facial deformities and autoimmune deficiency." (PMID 32831648, 2020).
cutaneous melanoma (1 paper, 2018). A primary melanoma arising from atypical melanocytes in the skin. "POLE2 is a subunit of the polymerase epsilon enzyme complex; we have previously demonstrated that a deleterious variant in another member of this complex, POLE, was associated with cutaneous melanoma development." (PMID 29641532, 2018).
IMAGe syndrome (1 paper, 2022). IMAGe syndrome is characterized by the association of intrauterine growth retardation, metaphyseal dysplasia (and short limbs), adrenal hypoplasia congenita, and genital anomalies. "Notably, patients with hypomorphic mutation of POLE, in FILS and IMAGe syndromes, and POLE2 exhibit a characteristic reduction in the number of B lymphocytes and variable degrees of immunodeficiency." (PMID 35649380, 2022).
Immunodeficiency (1 paper, 2022). Failure of the immune system to protect the body adequately from infection, due to the absence or insufficiency of some component process or substance. "Similarly, mutations of the essential non-catalytic subunit of Polε, POLE2, have been associated with a severe combined immunodeficiency with facial dysmorphism and impaired growth." (PMID 35649380, 2022).
Kidney Clear Cell Carcinoma (1 paper, 2021). "The datasets of POLE2 expression in The Cancer Genome Atlas Kidney Clear Cell Carcinoma (TCGA-KIRC) and International Cancer Genome Consortium (ICGC) databases was selected and the correlation between POLE2 and various clinicopathological parameters was analyzed." (PMID 33644060, 2021).
prostate carcinoma (1 paper, 2016). A carcinoma that arises from epithelial cells of the prostate gland. "A number of the top genes identified in this study have previously been implicated in prostate cancer development and progression, Gleason grade, metastases and biochemical recurrence; including CANT1, FBP1, RRM2, POLE2, PDE4D, and ALDH1A3." (PMID 27980733, 2016).
squamous cell lung carcinoma (1 paper, 2024). A carcinoma arising from squamous bronchial epithelial cells. "In squamous cell lung cancer, the up-regulated expression of the POLE2 gene was inversely correlated with survival and immune infiltration." (PMID 38370377, 2024).